HIF1A (hypoxia inducible factor 1 subunit alpha)
Diseases named in the same sentence as HIF1A in open-access papers (continued):
Sharing a sentence is not in itself a finding about the gene and the disease.
Stroke (continued). "Serum HIF‐1α levels were higher in stroke patients than controls." (PMID 34708885, 2021). "For instance, neuronal HIF-1α knockout mice show neuroprotection in a model of stroke." (PMID 34447792, 2021). "The expression level of HIF-1α induced by stroke is related to the ischemic duration." (PMID 34966392, 2021). "Previous studies have reported HIF-1α activation to alleviate brain injury induced by stroke." (PMID 34205911, 2021). "Consistently, stroke patients recently admitted to the hospital showed a high expression of HIF-1α." (PMID 34447792, 2021). "Such therapeutic effect of ADPN on stroke could be attributed to the boosting of antioxidant capacity by HIF-1α in neurons." (PMID 34336097, 2021). "In addition, diabetic mice treated with long-term insulin showed similar HIF-1α levels in the contralateral and ipsilateral hemispheres of the brain in stroke rats." (PMID 34966392, 2021). "Another factor that may be involved in determining the outcomes of post-stroke exercise regimens is hypoxia-inducible factor-1α (HIF-1α)." (PMID 32670026, 2020). "Additionally, the role of VEGF as an endogenous factor of recovery after CNS damage is proven in stroke, where ischemia induces the stabilization of HIF-1α as a transcriptional activator of VEGF." (PMID 32581664, 2020). "Furthermore, we have demonstrated that BM-MNC transplantation after stroke activates Hif-1α in endothelial cells via gap junction mediated cell–cell interaction followed by activation of angiogenesis and suppression of autophagy in murine model." (PMID 32595487, 2020). "Indeed, multiple Hypoxia-inducible factor 1alpha (HIF-1α)-induced miRNAs, called hypoxia-regulated microRNAs (HRMs), have been shown to modulate post-stroke angiogenesis by targeting the vascular endothelial growth factor A (VEGF-A) pathway." (PMID 30678250, 2019). "It is our opinion that this may probably be due to the fact that HIF-1α could be a trigger when hypoxia occurs, however as the stroke processes versus the re-oxygenation its values decreases due to the reoxygenation of the tissue." (PMID 30678250, 2019). "Moreover, treatment with a HIF-1α inhibitor suppresses the stroke-related increase in HIF-1α and reverses the neuroprotective effect of OA." (PMID 30002617, 2018). "In addition, in the present study, BMSCs remarkably inhibited pro-inflammatory cytokines generation and promoted neurotrophin secretion, these data further confirmed the protective roles of Hif-1α-overexpressing BMSCs in rat MCAO stroke model." (PMID 28424584, 2017). "Indeed, whilst ablation of neuronal HIF-1α and HIF-2α is reported to be beneficial in the hours following stroke, loss of HIF-1α and -2α correlated with increased apoptosis and reduced sensorimotor function in later stages." (PMID 28968430, 2017). "The possible mechanisms for developing brain cancer in stroke patients may arise from the overproduction of HIF-1α by ischemic brain tissue in stroke patients." (PMID 29312585, 2017). "HIF-1α is a key component of the cells' response to hypoxia, and the oxygen-labile HIF-1α protein is known to be induced in the central nervous system after focal ischemia caused by tumors or strokes." (PMID 25849940, 2015). "Based on the presented data here, the PrPc–proteasome–HIF-1α link might represent a promising target for restorative stroke therapies." (PMID 26673668, 2015). "GSNO treatment of stroke confers not only this neuroprotection against neuroinflammatory insults but also induces angiogenesis via stimulating VEGF through the stabilization of the HIF-1α/VEGF pathway." (PMID 27668143, 2015). "Considering that HIF-1α is degraded by the proteasome and inhibition of proteasomal activity reduces ischemic brain injury, we next evaluated HIF-1α abundance in western blots, which was significantly reduced by PrP−/− and significantly increased by PrP+/+ at 24 h post-stroke." (PMID 26673668, 2015).
Stroke (continued). "Therefore, regulation of the PTEN mRNA is likely to regulate signaling downstream of HIF-1α in stroke indirectly." (PMID 24961318, 2013). "In the early subacute phase, i.e., 7 days after stroke, the concentration of IL17α in blood serum reached its peak, which correlated with the increased expression of HIF1α in the pig brain, supporting the theory that HIF1α is an activator of the transcription factor for IL17α (RORγt)." (PMID 40332314, 2025). "Therefore, our results presenting upregulated VEGF expression on day 7 post-stroke may confirm HIF1α’s pro-angiogenic role." (PMID 40332314, 2025). "Therefore, we speculated that increased HIF‐1α levels would protect against myocardial damage and mediate inflammation, thereby reducing the risk of CES stroke." (PMID 40022282, 2025). "Furthermore, HIF-1α activation can modulate glial activity 12 days post-stroke." (PMID 34205911, 2021). "Besides, HIF-1α induction reduced the infarct volume 24 h and 48 h post-stroke." (PMID 34205911, 2021). "Similarly, using PHD inhibitors for HIF-1α stabilization 6 h prior to stroke was neuroprotective." (PMID 34447792, 2021). "To examine whether the protective effect of HIF-1α after stroke is achieved by modulating inflammation, we evaluated the expression levels and mRNA of pro-inflammatory cytokines (iNOS, TNF-α, NF-κB and p-IκBα/IκBα), and anti-inflammatory cytokines (IL-10) in the ischemic brain." (PMID 34205911, 2021). "Therefore, HIF-1α may protect brain tissue post-stroke by modifying inflammatory and glial responses in brain tissue 12 days post-stroke." (PMID 34205911, 2021). "Moreover, along with thiamine administration, use of HIF-1α inhibitors such as YC1 may limit TD associated astrocyte death, similar to that following stroke." (PMID 29045486, 2017). "Furthermore, to explore the potential mechanism for developing malignant glioma in stroke patients, we investigated the expression of hypoxia key regulator HIF-1α using IHC staining in the tumor specimens surgically removed from the malignant glioma patients previously with or without stroke." (PMID 29312585, 2017). "So the possible mechanism of the primary GBM development may be due to stroke via HIF-1α pathway." (PMID 29312585, 2017). "In summary, we report that HIF-1α in microglia after stroke may facilitate phagocytosis and other microglial functions including chemotaxis, ROS production, and TNF-ɑ production through CD36 and/or MFG-E8 hence interfering with adult neurogenesis in the acute phase of ischemic stroke." (PMID 29340071, 2017). "Strikingly, HIF-1α expression is significantly decreased in Prnp-/- and increased in Prnp+/+ mice at 24 h post-stroke suggesting that PrPc might exert its neuroprotective effects against hypoxic damage in vivo via direct or indirect regulation of HIF-1α and hence LDH-A/lactate." (PMID 28066187, 2016). "Therefore, regulating the expression of HIF-1α by using its endogenous regulator, miR-335 could prove beneficial in stroke outcome." (PMID 26030758, 2015). "This raises the intriguing possibility that STI-1 may be a downstream mediator for the myriad of hypoxic responses triggered by HIF-1α, especially in relation to hypoxic preconditioning-induced cytoprotection against stroke, heart failure, liver failure, kidney failure and so forth." (PMID 23836498, 2013). "The ROS/HIF-1α/β-catenin signaling contributes to delayed hyperbaric oxygen (HBO)-facilitated neurogenesis and neurofunctional recovery after stroke." (PMID 40653468, 2025). "The enhanced expression of HSP60 on day 7 in pigs corresponded with HIF1α, NF-κβ and TNFα allowing for the presumption of a role for HSP60 in maintaining or triggering the inflammatory response after stroke." (PMID 40332314, 2025).
Stroke (continued). "Proper inactivation of HIF-1α may contribute to the reduction in inflammasomes and cell damage and to enhanced mitochondrial function through the transcriptional regulations and post-modification of target molecules in neurodegenerative diseases, such as stroke, TBI, and AD." (PMID 38674050, 2024). "HIF-1α functions as a key mediator of NSPC function under normal conditions and in stroke, playing a central role in regulating NSPC responses to hypoxia, metabolism, and the maintenance of the vascular environment of the NSC niche." (PMID 36835292, 2023). "Genes involved in key signaling processes after stroke, including Il-10, Il-12, Hmgb1, Il-13, p38 MAPK, HIF1α, Stat3, and Il-4, were inhibited by NPD1 + RvD1." (PMID 37270727, 2023). "HIF1A and CASP3 pathways, as the stroke-related essential genes, are involved in autophagy and apoptosis after cerebral ischemic injury." (PMID 36496986, 2022). "HIF-1, including HIF-1α and HIF-1β, is an important regulator of hypoxia in stroke and participates in the pathological process of stroke by regulating glucose metabolism, angiogenesis, erythropoiesis and cell survival." (PMID 36277910, 2022). "Consistent with these previous studies, we also found that HIF-1α and LDHA, triggered by inflammatory and hypoxic responses, strikingly increased in perioperative stroke mice compared with stroke-only mice and sham mice." (PMID 35799259, 2022). "For instance, the STAT 3/HIF-1α/VEGF signaling pathway can be activated by the inhibition of Calpain-1 activity and consequent promotion of astrocytic neurogenesis, which improves stroke prognosis." (PMID 34966392, 2021). "In order to investigate the role of HIF-1α in exogenous ADPN-induced cerebral protection after experimental stroke, the recombinant AAV containing HIF-1α siRNA was applied." (PMID 34336097, 2021). "In this article, we introduce the functions of HIF-1α and its downstream target genes in different cells in the NVU during stroke." (PMID 34966392, 2021). "Specifically, the intense exercise protocol showed a significant increase in the mRNA expressions of HIF-1α, TrkB, CREB, BDNF, and NGF at different time points as compared to the stroke groups." (PMID 33625674, 2021). "The real-time RT-PCR results showed that mRNA expression of HIF-1α and HIF-2α were more than 3-fold upregulated 48 h post-stroke in the ischemic brain, whereas RIPC decreased nearly 50% of HIF-1α and 60% of HIF-2α mRNA expression." (PMID 32210788, 2020). "In this study, we aimed to provide insights into the roles of HIF-1α and HIF-2α in RIPC protection in aged stroke rats and explore the regulatory mechanism of inflammatory cytokines." (PMID 32210788, 2020). "HIF1α was only upregulated after ischaemic stroke and significantly upregulated after DCAL stroke when compared to MCAo." (PMID 33097782, 2020). "Immunostaining data revealed that increased expression of HIF1α, ZEB2, and TRPC6 in glomeruli from stroke-induced rats." (PMID 31784544, 2019). "Overall our results establish that TRPC6 is a novel target of HIF1α/ZEB2 axis and that transduces stroke-induced ischemia-hypoxia injury in podocytes." (PMID 31784544, 2019). "This work identifies HIF-1α-mediated transcription of STI-1 and PrPc interaction as leading to BMDCs recruitment into ischemic brains following stroke in both patients and animal models of stroke, highlighting novel neuroprotective possibilities." (PMID 23836498, 2013). "Hypoxia-inducible factor-1α (HIF-1α) may modulate the inflammatory response through the NLRP3 inflammasome complex, thereby affecting pyroptosis after stroke." (PMID 38102696, 2023).
Stroke (continued). "HIF-1A is considered an important target for stroke treatment, and studies have demonstrated that inhibiting HIF-1A can increase the mortality and cerebral infarction size of stroke." (PMID 36399471, 2022). "For instance, siRNA knockdown of PUMA prevented HIF-1α-induced cell death in hippocampal neuronal cells, while knockdown of NOXA rescued cells from hypoxia-induced cell death and decreased infarct volume in stroke." (PMID 35628182, 2022). "Another limitation of our research is that we only focused on the effect of NLXTD on targeting the HIF-1α/VEGF signaling pathway in promoting angiogenesis after 7 days of a stroke, which lacked a dynamic observation of indicators." (PMID 35449809, 2022). "After stroke injury, PK2 induction is biphasic: 1–3 h after injury, glutamate induces an initial PK2 overexpression, while a second peak is observed after 24 h, which is due to the activation of hypoxia-inducible factor 1 alpha (HIF1α)." (PMID 34829877, 2021). "Serum levels of miR‐210 were significantly different between the time of admission and 3 months after the stroke incidence (p = 0.0111), but serum HIF‐1α did not markedly change at different time points." (PMID 34708885, 2021). "Second, RIPC has been shown to decrease the expression of HIF-1α and HIF-2α in the ischemic brain and to decrease the protein levels of pro-inflammatory cytokines IL-1β and IFN-γ in both the blood and brain 48 h post-stroke." (PMID 32210788, 2020). "HO-1 is an upstream factor for HIF-1α stabilization in the periinfarct region of ischemic stroke brain of mice and HIF-1α induction in ischemic neurons may play a therapeutic role by inducing VEGF, a potent angiogenic and neurogenic factor, in a stroke model." (PMID 32218342, 2020). "Similarly, the western blotting (WB) results and the statistical data showed that RIPC attenuated the protein expression of HIF-1α and HIF-2α in the ischemic brain 48 h post-stroke." (PMID 32210788, 2020). "Interestingly, in stroke-induced rats, we observed elevated expression of ZEB2 along with HIF1α in the glomerular podocytes." (PMID 31784544, 2019). "Of note, although evidence associating EDA and HIF-1α in cardiac diseases has not been documented in current literature, EDA has been found to regulate HIF-1α in neurological studies related to stroke." (PMID 29765498, 2018). "APX3330 inhibits NFκB and HIF-1α activity, and can potentially attenuate neuroinflammatory responses and post ischemic angiogenesis, which makes APX3330 a suitable candidate for stroke therapy in DM rats." (PMID 29896433, 2018). "HO-1 is an upstream factor for HIF-1α stabilization in the periinfarct region and HIF-1α induction in ischemic neurons may play a therapeutic role by inducing VEGF in a stroke model." (PMID 30585210, 2018). "Compared with the malignant glioma previously without stroke, the HIF-1α expression significantly increased in the GBM previously with stroke." (PMID 29312585, 2017). "Compared with malignant glioma previously without stroke, HIF-1α expression significantly increased in GBM previously with stroke." (PMID 29312585, 2017). "However, neuronal-specific knockdown of HIF-1α and HIF-2α expression was shown to decrease infarct size and improve neuronal survival in the early acute stages of middle cerebral artery occlusion, suggesting HIF signalling could contribute to stroke-associated damage." (PMID 28968430, 2017). "In contrast, no staining of HIF-1α was seen in 100% (3/3) of GBMs previously without stroke and 100% (3/3) of grade I astrocytomas." (PMID 29312585, 2017). "Further, the KG diet upregulated the HIF-1α and interleukin (IL)-10 expression and inhibited thioredoxin-interacting protein (TXNIP), NOD-like receptor family pyrin domain-containing 3 (NLRP3) inflammasome activation and pro-inflammatory cytokine expression compared to SD-fed mice after stroke." (PMID 40272769, 2025).
Stroke (continued). "Cosin-Roger and his colleagues discovered one binding site for HIF-1α at −150 in the NLRP3 promoter through chromatin immunoprecipitation; HIF-1α regulates inflammatory responses through the NLRP3 inflammasome, thus influencing both apoptotic and pyroptotic cell death after stroke." (PMID 35132350, 2022). "However, the role of HIF-1α in BBB damage within the first several hours after stroke onset is not known." (PMID 28855859, 2017). "Our results indicated that HIF-1α could be a potential target able to control the progress of RGC survival-related eye disease and a crucial target for drug development in treatments of cancer, heart disease, and stroke." (PMID 22736948, 2012). "Here, we also showed that HBMEC exposed to OGD demonstrated up-regulated HIF-1α and Hsp70 concomitant with MCP-1/MMP-2 and Tie-2 gene and protein expression suggesting at least some of the proteins may be produced by EC de novo after stroke." (PMID 19292924, 2009). "Tumor specimens removed from 8 patients (2 GBMs previously with stroke, 3 GBMs previously without stroke and 3 grade I astrocytomas) with histologically-proven, surgically-treated malignant glioma were examined by IHC staining for HIF-1α, a key hypoxic regulator." (PMID 29312585, 2017). "Of note, pretreatment with BSc2118 also resulted in increased protein expression of HIF-1α and PACAP-38 24 h post-stroke in both WT and PrP−/− mice (data not shown)." (PMID 26673668, 2015). "Thus, Wnt/HIF1α signaling in mature ECs may not be critical for barrier formation, but may play an indirect role in a context-dependent manner, for example via HIF1α/VEGFA signaling during hypoxic conditions in diseases such as stroke and cSVD." (PMID 38147228, 2024).